EGFR (epidermal growth factor receptor)
Diseases named in the same sentence as EGFR in open-access papers (continued):
Sharing a sentence is not in itself a finding about the gene and the disease.
infection (continued). "We conclude that the EGFR pathway is essential for the proper execution of anoikis in response to infection." (PMID 21176204, 2010). "We conclude that a wild-type level of EGFR pathway activity is required in enterocytes for the proper coordination of their delamination and anoikis upon infection." (PMID 21176204, 2010). "To investigate further the role of EGFR in the delamination process, we examined histological sections of guts upon infection." (PMID 21176204, 2010). "We observed that, upon infection, reduction of EGFR pathway activity in enterocytes decreased the sloughing of cells from the epithelium and led to apoptosis of enterocytes still within the layer." (PMID 21176204, 2010). "Upon simultaneous knock-down of CHC and CAV-1 the amount of EGFR located at the cellular surface, was only reduced about 3% after infection indicating that internalisation is greatly dependent on these two factors." (PMID 20844577, 2010). "This prolonged EGFR activation and signalling would ensure that the infected cell receives a sustained survival signal that antagonizes infection-induced cell death." (PMID 19388902, 2009). "Together, our results demonstrate that VGF signalling via the EGFR is sufficient to promote F1L-independent cell survival during infection." (PMID 19388902, 2009). "The amount of both total and phosphorylated forms of EGFR was dramatically reduced in cells upon PilC1-mediated infection." (PMID 19718432, 2009). "In the case of PilC2-mediated infection, EGFR phosphorylation response to EGF stimulation was slightly lower in comparison to non-infected control cells." (PMID 19718432, 2009). "Because the total protein level of EGFR prior to EGF stimulation was low in cells infected through PilC1 (left panel-), the strong reduction in EGFR phosphorylation was probably due to the depletion of the total EGFR pool upon PilC1-mediated infection." (PMID 19718432, 2009). "Infection with the resulting double mutant virus (ΔF1L/VGF) leads to inhibition of phosphorylation of the EGFR, indicating that the virus, like ΔVGF, was unable to induce growth factor signalling." (PMID 19388902, 2009). "We conclude that VGF stimulates an epidermal growth factor receptor-MEK-dependent pro-survival pathway that synergizes with F1L to counteract an infection-induced apoptotic pathway that predominantly involves the BH3-only protein Bad." (PMID 19388902, 2009). "albicans infection modulates the host ubiquitin system, including direct effects on EGFR, highlighting a novel aspect of host-fungal interactions.IMPORTANCECandida albicans is a common fungal pathogen that causes both mucosal infections, such as thrush, and life-threatening systemic diseases." (PMID 41524399, 2026). "Also, taFv-EGFR expression in all cell lines was stronger after infection with Ad5/3-DMTtE than after infection with Ad5/3-tE." (PMID 41552759, 2026). "The early activation of PI3K/Akt, as exemplified by EtMIC4’s co-option of upstream EGFR signaling, constitutes a key molecular strategy whereby Eimeria hijacks host survival pathways to secure a viable intracellular niche during the initial phase of infection." (PMID 41463813, 2025). "In addition, infection with bacteria that synthesize the OmpX protein enhances the expression of EGFR and β1 integrin involved in the invasion of S. proteamaculans." (PMID 40362195, 2025). "Through high-resolution immunofluorescence microscopy, we observed strong colocalization of JEV envelope particles with EGFR at early times of infection, with the maximum colocalization observed at t = 0 min, highlighting the possibility of a direct association between the two." (PMID 41401233, 2025). "Additionally, BHY cells (human bone invasive OSCC) respond to bacterial challenges by increasing defensin expression, suggesting a link between infection and tumorigenesis via EGFR-NF-κB." (PMID 40924302, 2025).
infection (continued). "Notably, treatment of HFFs with the VGF peptide upon vΔVGF infection successfully rescued EGFR phosphorylation to levels comparable with those seen in WT-VACV infection." (PMID 39817770, 2025). "In addition, EGFR is involved in the infection of host cells by bacterial pathogens through various mechanisms." (PMID 40362195, 2025). "In both models, the EGFR pathway, crucial to stem cells and progenitors proliferation and differentiation, is dysregulated by Salmonella, suggesting that repeated infections might have consequences on crypt integrity and further oncogenesis." (PMID 38956132, 2024). "Infection with bacteria leads to the formation of EGFR-carrying endosomes." (PMID 38892348, 2024). "Accelerated EGFR internalization in HEV-replicating cells indicates HEV-dependent heightened EGFR flux or reduced receptor recycling capacity due to the diminished EGFR pool upon infection." (PMID 38856640, 2024). "Recent studies have demonstrated that among the 21 Polymorphic Membrane Proteins (Pmps) of C. psittaci, Pmp22D, Pmp8G, and Pmp17G possess adhesive properties and activate intracellular internalization by recognizing epidermal growth factor receptor (EGFR) during infection." (PMID 39541409, 2024). "Additionally, RABV induces biphasic dynamics of epidermal growth factor receptor (EGFR)-phosphatidylinositide-3 kinase (PI3K)-Rac1 signaling at early infection and impedes Rac1-p21-activated kinase 1 (Pak1) transduction later." (PMID 38809020, 2024). "To assess whether the activated EGFR pathway is involved in the infection efficacy of SARS-CoV-2 variants, we used osimertinib, an EGFR-TKI, to inhibit the activated EGFR pathway." (PMID 39291996, 2024). "The inhibition of the EGFR pathway can prevent the final infection of FMDV." (PMID 38512977, 2024). "This could indicate a partial rescue of EGFR synthesis during infection or changes in protein stability." (PMID 39621795, 2024). "In line with a critical role for EGFR in Spike-RBD signaling that we identified, KD of EGFR also led to a significant reduction of Spike-PP infection, shown by a 52.8% reduction of GFP-positive cells when compared with the scramble controls (NC) 24 h postinfection." (PMID 37402592, 2023). "In addition, similarly to our data, the Salmonella Rck membrane protein has been reported to bind and activate EGFR and its mediated signaling resulting in receptor/bacteria co-internalization and cell infection." (PMID 37112680, 2023). "EGFR was up regulated gradually from day 3 to day 6 and day 9-post infection." (PMID 37270623, 2023). "trachomatis infection: regulation of the cell cycle and expression of EGFR and α5β1-integrin." (PMID 37513730, 2023). "Only longer infection induced EGFR phosphorylation, which increased until 8h p.i.." (PMID 38033162, 2023). "In addition, the EGFR-specific inhibitor erlotinib also reduced the infection of Spike-PP by 40.7% at a concentration of 5 μM and by 67.3% at a 10 μM concentration." (PMID 37402592, 2023). "EGFR was more abundant than IL-17RA on the cell surface from day 6 to day 9 post infection." (PMID 37270623, 2023). "Nevertheless, EGFR responses are better lined up with p38 response in both strain infections." (PMID 35720274, 2022). "Thus, antagonizing the EGFR/EGR1 signaling enables CMV to maintain a productive infection and suggests EGR1 serves a pro-viral role during CMV infections." (PMID 36338037, 2022). "Then, we investigated whether activated EGFR could also affect the infection of other CNS-invading flaviviruses in hBMECs." (PMID 35847084, 2022). "REG4 is involved in infection and inflammation by enhancing macrophage polarization to M2, via activation of epidermal growth factor receptor (EGFR)/Akt/cAMP-responsive element binding and the killing inflammatory Escherichia coli, and closely linked to tumorigenesis." (PMID 36172286, 2022). "Whether EGFR expression level is higher in some HPV subtypes or lower in other subtypes during infection still need to be explored." (PMID 34646755, 2021).
infection (continued). "In addition, PDGFR is not reported to be expressed on freshly-isolated blood monocytes or freshly-isolated CD34+ HPCs suggesting that the gB/EGFR interaction plays a key role in the infection of these cell types." (PMID 34025614, 2021). "Additionally, levels of genes associated with the EGFR/MAPK pathway, such as argos (aos), rhomboid (rho), Sox21a, and string (stg), appeared increased following Ecc15 infection in control midguts in a RalA-dependent manner." (PMID 34096503, 2021). "We found many variables associated with ANC, including mutational status of EGFR/ALK, concurrent chemotherapy, concurrent infection, high level of troponin or other inflammatory markers, baseline levels or changes in electrolytes, and changes in lab tests associated with kidney or liver function." (PMID 33882890, 2021). "At the same time, a total amount of EGFR in cells was increased during infection (insert)." (PMID 34948042, 2021). "Further, the inhibition of EGFR leads to reduced infection by influenza A and rhinovirus." (PMID 34436155, 2021). "Downregulation of EGFR by Nec-1s in the lung organoids infected by SARS-CoV-2 may regulate an early immune response against the infection." (PMID 34663909, 2021). "EGFR is an important receptor for efficient infection and establishment of latency in CD34+ HPCs." (PMID 34663377, 2021). "Thus, anti-viral drug discovery requires a more nuanced understanding of EGFR-regulated mechanisms contributing to the infection process of multiple biologically diverse animal cell viruses." (PMID 35083168, 2021). "Interestingly, we saw that a bi-phasic induction of LDs occured following dsRNA viral mimic infection, firstly mediated by EGFR in an IFN independent mechanism, with the second wave, being induced via activation of the JAK/STAT pathway by IFN." (PMID 34527863, 2021). "In the absence of protection by the C46 peptide (ITS06-deltaCD3ζ), the ratio of the percentage of GFP+ cells among EGFR+ cells over the percentage of GFP+ cells among EGFR− cells was around 1, because EGFR+ and EGFR− cells would be similarly susceptible to infection." (PMID 34485613, 2021). "We found that about 20% of IAVs colocalized with EGFR, and that efficient infection depended on available plasma membrane EGFR and could be inhibited by EGFR-specific kinase inhibitors." (PMID 32639985, 2020). "Interestingly, a second transcriptomic analysis unveiled the activation of epidermal growth factor receptor (EGFR) signaling in alveolar epithelial cells, which is phosphorylated upon in vitro infection of these cells with Rhizopus delemar spores." (PMID 32604972, 2020). "Indeed, pretreatment of the cells with the EGFR inhibitor AG1478 led to an overall increase in SUMO1 levels upon infection." (PMID 32994335, 2020). "HCMV transcriptionally downregulates EGFR during lytic infection and targets EGFR for turnover but utilizes the receptor during entry into monocytes and CD34+ HPCs, where EGFR signaling is critical for trafficking of the viral genome to the nucleus (31, –, 34)." (PMID 32759334, 2020). "As such, this work supports that EGFR is concomitantly activated at late stages of infection." (PMID 32846937, 2020). "Using these stable cell lines, we examined the effect of HER2 and EGFR on EBOVΔVP30 infection." (PMID 33052961, 2020). "EGFR surface levels began to decrease by 12 hpi and were reduced to ~60% of uninfected (0 hpi) cells by 24 hpi, and remained between 50 and 60% of uninfected cells for the remainder of the infection time course." (PMID 31725811, 2019). "(A) EGFR blocking-antibody Cetuximab decreases HPV16 PsVs infection rate." (PMID 31107240, 2019).
infection (continued). "Finally, CMV replication in fibroblasts stimulates WT1 expression, which competes antagonistically for EGR1 targets, including EGFR, and indicates another mechanism by which the virus antagonizes EGFR/EGR1 signaling for productive infection." (PMID 31725811, 2019). "It was suggested that anti-microbial peptides could function as a molecular link between tumorigenesis and infection since human defensins affect cell proliferation via Epidermal Growth Factor Receptor (EGFR)-dependent signaling." (PMID 30671195, 2019). "Thus, the role of EGFR is dependent on the severity of the current infection, indicating a role in pathogenicity as predicted by our OMICS studies." (PMID 31616667, 2019). "Thus, we used the EGFR blocking-antibody Cetuximab to confirm the functional requirement of EGFR in HPV16 PsVs infection." (PMID 31107240, 2019). "In the first step, we investigated whether infection with E. coli or AREG stimulation would affect the number of EGFR-positive cells in our PBMO and CBMO populations." (PMID 32082070, 2019). "The lack of a transcriptional downregulation in our study may reflect differences in the virus strain used for infection or the cell type, and leaves open the possibility that other viral factors contribute to the diminishment of EGFR levels." (PMID 31725811, 2019). "Rather, the effect of DN EGFR is to reduce the foci of infection in neural endothelial cells." (PMID 31119109, 2019). "Together these data indicate that while infection sustains or induces basal levels of EGFR signaling at early times, EGFR and both the MEK/ERK and PI3K/AKT downstream signaling nodes become progressively less responsive to stimulation in the productive infection." (PMID 31725811, 2019). "Since we demonstrated that both ERK1/2 and Akt phosphorylations are induced by infection-mediated activation of EGFR, we wanted to investigate whether these signaling events mediate phosphorylation of the protein BAD through AREG signaling." (PMID 32082070, 2019). "Additionally, we found candidalysin to be largely responsible for the shedding of several ErbB ligands during infection, all of which ligate EGFR." (PMID 31127085, 2019). "Weight loss was significantly worsened when EGFR was inhibited during low-path infection as well as during low dose infection treatment with a highly pathogenic strain, all of which were non-lethal infections." (PMID 31616667, 2019). "Moreover, we propose to evaluate the use of inhibitors that target specific pathway, such as the EGFR inhibitor erlotinib, that is altered by the virus and consequently induces the epigenetic changes following the infection." (PMID 31216276, 2019). "However, similar to infection in fibroblasts, basal levels of phosphorylated EGFR and downstream pathways were sustained or increased by CMV infection (PathScan)." (PMID 31725811, 2019). "A recent report has shown that, under certain circumstances Th2 cells can express EGFR allowing them to produce inflammatory cytokines that may protect the host from infections." (PMID 31921216, 2019). "Compared to C. albicans SC5314 infection, EGFR triggers two proteins BPHL and AVEN." (PMID 30769958, 2019). "The infection progression associated with essential epigenetic modifications in two strains of C. albicans such as ARRB2, CDH1, HSP90B1, EGFR and ERBB2, and host miRNA repressing on pathogens genes are mostly identified in core HPCNs by our systems biology approach." (PMID 30769958, 2019). "However, as we did not specifically address the mechanism in the course of this study, future work will focus on clarifying the role of TNF-α in infection-mediated EGFR upregulation." (PMID 30524196, 2018). "Furthermore, we found that the S. suis serotype 2 strain also induced EGFR activation, as well as dimerization of EGFR to mediate neuroinflammatory responses during its infection." (PMID 30687645, 2018).
infection (continued). "However, when it comes to infection of sites of latency, great attention has been given to the possible role of EGFR during this process, particularly in monocytes." (PMID 29547547, 2018). "Inhibition of EGFR reduced the damage caused by TGEV to intestinal epithelial cells, ameliorated the loss of intracellular Na+ caused by TGEV infection, restored the normal function of membrane transporter NHE3, and promoted the transport of extracellular Na+ into cells." (PMID 30483239, 2018). "EGFR signaling is activated during in vitro infection of airway epithelial cells." (PMID 30108171, 2018). "To date, several bacterial pathogens have been reported to target EGFR through different mechanisms to facilitate their infection of host cells, including Neisseria gonorrhoeae, N. meningitidis, Helicobacter pylori, Haemophilus influenzae, and Klebsiella pneumonia." (PMID 30687645, 2018). "Interestingly, infection of cells with VSV, which is known to be infectious and pathogenic in humans, also led to the downregulation of CD9, CD81, CD151 and EGFR." (PMID 29121670, 2017). "In consistent with previous results, two later meta-analyses also showed that EGFR-monoclonal antibodies significantly increased the risk of developing severe infections but not for fatal adverse events." (PMID 28107192, 2017). "EGFR activation has been shown to be essential for VACV-infection of HeLa cells." (PMID 29121670, 2017). "As far as we known, our study is the first large meta-analysis to show a significantly increased risk of developing EGFR-TKIs related infection (Peto OR 1.48, p = 0.006) in NSCLC patients, but not for high-grade and fatal infectious events." (PMID 28107192, 2017). "Furthermore, RSV fusion protein interacts with epidermal growth factor receptor (EGFR) in a strain-specific manner, suggesting that EGFR is a co-factor for infection and that EGFR plays a role in RSV-induced mucin expression." (PMID 29162850, 2017). "Moreover, clinicians should treat NSCLC patients with any active infection before the initiation of EGFR-TKIs treatment." (PMID 28107192, 2017). "Furthermore, we recently demonstrated that epidermal growth factor receptor (EGFR) pathway is involved in this phenomenon and that this is an early event during infection." (PMID 28767704, 2017). "Upregulation of the transcript levels of EGFR was observed only upon an infection with H. pylori." (PMID 28180113, 2017). "The results showed that the longer EGFR-TKIs treatment, and the higher risk of infections with EGFR-TKIs, but this relationship was not statistically significant (P = 0.26)." (PMID 28107192, 2017). "Infection with such viruses will result in astrocytic EGFR hyperactivity." (PMID 28074274, 2017). "The difference in the expression of EGFR during infection and activation of HGEC was a discrepancy that has also been observed in human monocytes, reflecting the fact that live bacteria signaled mostly through TLR-2 and TLR-4, while purified LPS-Pg acted through TLR-2." (PMID 28748038, 2017). "Additionally, Spitz (Spi) and Keren (Krn), two EGFR ligands, are essential for ISC division via the EGFR/RAS/RAF/mitogen-activated protein kinase (MAPK) pathway after infection." (PMID 28923062, 2017). "Thus, in effect, via this EGFR-mediated licensing of Th2 cells, we observed a functional merger of the innate and adaptive immune responses at the site of infection in order to reach a sufficient mass at critical time points during infection." (PMID 29045902, 2017). "Therefore, Fip2 is essential for a successful infection as (i) it directly influences EGFR-mediated endocytosis and (ii) regulates the intracellular transport of the endocytosed EBs within their specific endosome." (PMID 28787457, 2017). "In conclusion, our study has demonstrated that treatment with EGFR-TKIs in advanced NSCLC is associated with an increased risk of all-grade infections, but not for high-grade and fatal infections." (PMID 28107192, 2017).